ESR1 (estrogen receptor 1)
Diseases named in the same sentence as ESR1 in open-access papers (continued):
Sharing a sentence is not in itself a finding about the gene and the disease.
breast tumors (continued). "The expression levels of GATA3 and ESR1, which are both the breast tumor-related genes, showed upregulation in tumor tissues compared with normal tissues." (PMID 31182966, 2019). "To date, ESR1 fusion transcripts that produce stable ESR1 fusion proteins have only been detected in metastatic breast tumors resistant to multiple lines of endocrine therapies." (PMID 31106278, 2019). "The WHIM16 PDX model also harbors ESR1 amplification, and ESR1 amplification was detected in a primary breast tumor from a patient with ER+ metastatic disease that regressed in response to E2‐based therapy." (PMID 31180176, 2019). "Amplification of the ESR1 locus results in overexpression of oncogenic ER protein in the breast and potentially reducing sensitivity of ESR1 amplified breast tumors to endocrine therapies and therefore likely leads to disease progression and metastasis." (PMID 31106278, 2019). "In a preliminary research, we revealed the significant association between ESR1 methylation and some reproductive factors such as FFTP in breast tumors." (PMID 30054444, 2019). "We also found non-significant positive correlations of CYP19A1 mRNA expression with ER status and with ESR1 mRNA expression in breast tumors." (PMID 29363090, 2018). "Three different receptors for estrogens have been identified in breast tumors, two nuclear receptors, ERα and ERβ, and a G-protein coupled estrogen receptor 1 (GPER) that initiates non-genomic effects of estrogens in the cytosol." (PMID 30687231, 2018). "Structurally related to ESR1, this protein is expressed in 80% of breast tumors, of which 55% are ESR1-positive and 35% are classified as triple-negative tumors (negative for ESR, progesterone receptor, and HER2 receptor)." (PMID 29949923, 2018). "Growth of breast tumors driven by ESR1 fusions at primary and metastatic sties can be suppressed with a CDK4/6 inhibitor." (PMID 30089255, 2018). "In some studies, the ESR1 promoter was found to be frequently hypermethylated whereas according to others, methylation of the ESR1 is a rather uncommon event in breast tumors." (PMID 28403857, 2017). "As a result, we found that ERα protein is significantly elevated in TLK2-high breast tumours (based on t-test, P=0.041), in spite of a slight increase of ESR1 transcript (based on t-test, P=0.158)." (PMID 27694828, 2016). "Based on this molecular taxonomy, breast tumors were broadly divided into 2 groups contingent on their expression of the estrogen receptor (ESR1, hereafter termed ER)." (PMID 25076125, 2014). "In contrast, transcriptional regulation of the ESR1 gene promoter was described in a number of studies to be an important mechanism for overexpression and maintenance of ER expression in breast tumors." (PMID 25149534, 2014). "We therefore measured the expression of miR-4728-3p, HER2 and ESR1 in a set of 19 Her2- and 19 Her2+ breast tumors by qPCR." (PMID 24828673, 2014). "In cell models of ERα-expressing breast tumors, ESR1 mRNA expression is driven predominantly by the proximal A promoter that encompasses −163/+1 base pairs relative to the transcription start site (TSS)." (PMID 24339902, 2013). "For this, we performed LCM to separately isolate the stromal (S) and epithelial tumor cell (T) areas from 10 breast tumor tissues (n = 9 ESR1 high, n = 1 ESR1 low) with sufficiently micro-dissectible fresh frozen tissue left." (PMID 22967435, 2012). "The luminal cluster predominantly harboring luminal breast tumors (ER/PR+, HER2+/−) was associated with strong overexpression of the estrogen receptor (ESR1) and the ERBB2 oncogene." (PMID 23049873, 2012). "MKI67 and TERT were significantly upregulated in the 23 DNA aneuploid breast tumors, while ESR1/ERα expression was similar in the diploid and aneuploid breast tumor subgroups." (PMID 21352579, 2011).
breast tumors (continued). "In this study, we used methylation-specific PCR (MSP) to analyse the methylation status in two regions of the CXCL12 promoter and ESR1 in tumour cell lines and in primary breast tumour samples, and correlated our results with clinicopathological data." (PMID 20109227, 2010). "In particular, the estrogen receptor-alpha (ERα) (ESR1) - present in tumor cells of about 70% to 75% of all breast tumors - is considered crucial because of its proliferation-inducing actions and for that reason is an important target for therapy." (PMID 21122099, 2010). "For example, the transcript data for EsR1 yields three clusters, which parallels the observation that primary breast tumors show varied expression of this protein." (PMID 19317917, 2009). "CDH1 and ESR1 are frequently concurrently methylated in breast tumors, a relationship also discernible in the present study." (PMID 18221536, 2008). "ESR1 A908G mutation-positive breast cancer was significantly associated with longer duration and recent use of OCs and with a first-degree family history of breast cancer, suggesting that OCs may interact with the ESR1 A908G mutant receptor in the development of some breast tumors." (PMID 17553133, 2007). "Clusters of genes containing some of the most important known markers of breast tumour phenotype are shown in greater detail: ESR1, MKI67, ERBB2, and TFF1." (PMID 17555561, 2007). "We identified that breast tumors in patients ≤ 60 exhibit lower ESR1 gene expression." (PMID 40666735, 2025). "We observed elevated GRPR and ESR1 mRNA levels in breast tumours expressing mutated, non-functional ECAD." (PMID 40500450, 2025). "This revealed that both EPI (e.g. LLGL2, CLDN4, KRT7, ST14) and MES (e.g. SNAI1, VIM, AP1M1) genes positively correlated with PIEZO1 expression across all quintiles, whilst markers of luminal breast tumors (ESR1, FOXA1, PGR) negatively correlated in all instances." (PMID 38632473, 2024). "Why 30–40% of breast tumours lack ESR1 expression is not fully known." (PMID 38236307, 2024). "Conversely, the brain and lung metastases shared the hotspot PIK3CA E545K mutation as well as all three ESR1 mutations (E380Q, D273N, D351H), which were not present in the matched primary breast tumor." (PMID 37377606, 2023). "However, breast tumors have been shown to progress due to acquired endocrine therapy resistance, including genomic alterations in estrogen receptor alpha (ESR1)." (PMID 35959983, 2022). "In addition, we measured the fusion transcripts in three sets of patient-matched normal breast and primary tumor carcinomas and four patient-matched sets of primary breast tumors and metastatic lymph nodes, also all ESR1-positive." (PMID 35151276, 2022). "Although estrogen receptors were not identified as predicted target miR-18a-5p, a negative correlation between miR-18a-5p and ESR1 expression was demonstrated in breast tumor cells and hepatocellular cancer, indicating a potential interaction of miR-18a-5p/ESR1." (PMID 36499183, 2022). "HCMV DNA and/or proteins in breast tumors have been associated with higher tumor grade, invasive breast cancer, and negative expression of the estrogen receptor-1 (ER), progesterone receptor (PR) and human epidermal growth factor receptor 2 (HER2)." (PMID 35267456, 2022). "Estrogen receptor–positive breast tumors, which initially respond effectively to endocrine therapy, progress due to acquired endocrine therapy resistance, including genomic alterations in estrogen receptor alpha (ESR1)." (PMID 35959983, 2022). "In addition, ESR1 expression is strongly negatively correlated with DNA methylation downstream of the major transcription start site in the TCGA breast tumor dataset." (PMID 34831189, 2021).
breast tumors (continued). "Using RNA sequencing of primary breast tumor samples taken at surgery and with a detection limit of minimum 2% MAF, the overall frequency of ESR1 ET resistance mutations in the population-based SCAN-B cohort was 0.9%, corresponding to 1.1% among the ER-positive tumors." (PMID 33937624, 2021). "A disease-specific microarray analysis of BRCA1-mutant breast tumor tissue over sporadic tumors expressing wild-type BRCA1 found that the expression of ESR1, which is a coding gene for ER alpha, was significantly lower in BRCA1-mutant tumor tissue than in sporadic tumor tissues." (PMID 35008774, 2021). "Importantly, these gene expression changes occurred in both ESR1+ and ESR1– cells within the same breast tumors, demonstrating for the first time a differential effect of estrogen on ESR1– cells." (PMID 34944995, 2021). "With respect to the therapeutic strategy for preventing ESR1 mutant-driven breast tumors, targeting these signaling pathways could be considered." (PMID 33233830, 2020). "In addition, CCDC170 was found to be tightly co-expressed with ESR1 in breast tumor biopsies and cells." (PMID 33291081, 2020). "A variety of ESR1 gene fusion transcripts have been identified in luminal breast tumors." (PMID 31106278, 2019). "However, a clear link between the presence of ESR1 amplifications in breast tumors and endocrine therapy resistance and metastasis remains to be shown." (PMID 31106278, 2019). "GATA3 is positively associated with ESR1, while TRPS1 is correlated with ERBB2 and might act as a potential modulator of chemosensitivity in breast tumor." (PMID 28423734, 2017). "The ESR1 promoter was hypermethylated in 41% of breast tumour samples." (PMID 20109227, 2010). "These preliminary results suggest that OCs may interact with the ESR1 A908G mutant receptor to drive the development of some breast tumors." (PMID 17553133, 2007). "Of the 653 breast tumors evaluated, 37 were ESR1 A908G mutation-positive and 616 were mutation-negative." (PMID 17553133, 2007). "In luminal breast tumors, characterized by estrogen receptor (ER) and/or progesterone receptor (PR) expression, mutations in enhancers and promoters of hormone-responsive genes, such as FOXA1 and ESR1, can disrupt hormone signaling, leading to endocrine therapy resistance." (PMID 41011238, 2025). "Importantly, the absence of detectable ESR1 mutations in primary breast tumors suggests that these mutations emerge through clonal selection during tumor evolution, enabling tumor cells to evade hormonal therapies." (PMID 40641933, 2025). "Indeed, a significant proportion of ESR1 LBD point mutations were identified in metastatic tumors that were extensively treated with AIs, suggesting that such mutations may be enriched in breast tumors upon AI treatment." (PMID 31106278, 2019). "Since the expression of exogenous ESR1 variant transcripts encoded by expression vectors is often initiated from non-endogenous human promoters that drive very high expression of constructs, it is unlikely to mimic the expression levels in human breast tumors harboring ESR1 point mutations." (PMID 31106278, 2019). "We detected ESR1 mutations in 21% (12/57) of MBCs, but could not detect them in primary breast tumors." (PMID 29166868, 2017). "However, subsequent studies performed mainly in primary breast tumors were not able to identify ESR1 mutations, and the potential clinical significance of the abnormality remained underappreciated for more than a decade." (PMID 28361033, 2017). "Similarly, 80 breast tumors with gene deletion contained mRNA levels higher than the 25th percentile, whereas 97 tumors with gene gain and five with gene amplification were found to have ESR1 mRNA levels lower than the cut-off used." (PMID 23923010, 2013).
breast tumors (continued). "Tumor cells exhibiting DNMT3b overexpression are likely to exhibit methylation-based aberrant gene expression; one study showed that breast tumors that overexpress DNMT3b are more likely to be ESR1-negative, display increased proliferation, and be associated with poor patient prognosis." (PMID 18221536, 2008). "In breast tumors, the EZH2-mediated repression of estrogen receptor 1 (GREB1), an ERα cofactor, results in tamoxifen resistance." (PMID 40006021, 2025). "All evidence suggests that ESR1, a downregulated gene, is a viable target in antitumor protein treatment of TNBC breast tumors, due to its effects and protein interactions." (PMID 39777114, 2024). "Among five subtypes of human breast tumors, the expression levels of TWIST1 and its upregulated genes, Vim and SNAI2, are the highest, while its repressed target genes, CDH2 and ESR1, are the lowest in ER−/HER2− breast cancers." (PMID 38893094, 2024). "In a preclinical model, at low doses, GDC-9545 promotes tumor regressions either as a single agent or combined with a CDK4/6 inhibitor in an ESR1 Y537S mutant PDX and in a wild-type ERα breast tumor model." (PMID 39767607, 2024). "TCGA database analysis of 1080 breast tumors showed that RNF2 expression was positively correlated with estrogen signaling target genes expression (PDZK1, TFF1 and ESR1)." (PMID 36271315, 2023). "Across the 112 684 cells analysed from primary breast tumours, a similar number of cancer cells expressed epithelial markers (EPCAM, CDH1 and ESR1)." (PMID 37691350, 2023). "RNA-seq analysis conducted by Veeraraghavan and colleagues on 990 primary TCGA breast samples identified the first ESR1 gene fusion, ESR1-e2>CCDC170, in a subset (2.1%) of Luminal B breast tumor samples." (PMID 36686845, 2022). "To further understand interplay between ESR1 and KRT gene expression, we determined expression of basal and luminal KRT genes in ER+ primary breast tumors." (PMID 35440136, 2022). "Though the choice of these loci was arbitrary for constructing the simulation, there is evidence that ESR1 and FOXA1 are highly co-expressed in breast tumors, and local-eQTLs of FOXA1 have been shown to be distal-eQTLs of ESR1." (PMID 33684137, 2021). "These ESR1 fusions transcripts, ESR1-e6>YAP1 and ESR1-e6>PCDH11X, were identified in patients with metastatic ER+ breast tumors that were pan-endocrine therapy resistant." (PMID 31106278, 2019). "In contrast to transcriptionally active ESR1 fusions, we also identified an in-frame ESR1-e6 fusion, ESR1-e6>NOP2 in a treatment naïve primary breast tumor that was transcriptionally inactive despite producing stable ESR1 fusion protein." (PMID 31106278, 2019). "Of the 35 upregulated genes, 5 were all related to breast tumor types: CASP8 (0.7-fold upregulation), CDH1 (1.21-fold upregulation), GATA3 (3-fold upregulation), ESR1 (3-fold upregulation) and FOXA1 (+ 2.89-fold upregulation)." (PMID 31182966, 2019). "Using candidate-gene approach, we examined the promoter methylation level of AR, ESR1, hTERT, MYC, RASSF1 and WNT1 in 69 male breast tumors and corresponding blood samples, 7 normal breast tissues and 8 normal lymph node samples." (PMID 29731982, 2018). "NEAT1 was also identified in a gene (ESR1, DKC1)–lncRNA (TERC and TUG1) interaction network in breast tumors from TCGA." (PMID 30545127, 2018). "In particular, we examined promoter methylation status of genes involved in signal transduction and hormone signalling, including AR, ESR1, hTERT, MYC, RASSF1 and WNT in male breast tumors, paired blood samples and normal tissues." (PMID 29731982, 2018). "The most common and clinically relevant feature is expression of the estrogen receptor alpha (ER-α; ESR1) transcription factor, which occurs in 70–80% of all breast tumors." (PMID 28320353, 2017). "Technically, we had already evaluated the quantitative performance of ddPCR using four representative ESR1 LBD mutant molecules, ESR1 Y537S, Y537N, Y537C, and D538G in breast tumor tissue." (PMID 27102299, 2016).
breast tumors (continued). "Several overlapping genes especially the ones present in all datasets (ESR1, FOXA1, KRT17) are known to play critical roles in the subtyping and carcinogenesis of breast tumors." (PMID 26404658, 2015). "These signature genes are densely connected, among which several, such as ESR1, FOXA1, NQO1, GATA1, ALDH3B2, keratins, are well-known players driving the heterogeneity and carcinogenesis of breast tumors." (PMID 26404658, 2015). "In their hierarchical clustering analyses, basal-like breast tumors were grouped together within a tight cluster showing high expression of basal cytokeratin genes (KRT5 and KRT17) and low expression of luminal estrogen receptor gene (ESR1)." (PMID 23049873, 2012). "An intra-chromosomal gene fusion involving the estrogen receptor alpha gene ESR1, and another involving the RPS6KB1 (Ribosomal protein S6 kinase beta-1) were recurrently expressed in a number of breast tumor cell lines and a clinical tumor sample." (PMID 22496636, 2012). "Means have also been established for statistical thresholds for ESR1, PR and ERBB2 transcript levels to assign their expression status in profiled breast tumor samples." (PMID 22022496, 2011). "In this study, we evaluated the methylation patterns of ESR1 and two CpG islands in the CXCL12 gene in breast tumour samples from Brazilian women." (PMID 20109227, 2010). "The ESR1 MSP results showed hypermethylation in the MDA-MB-436, MDA-MB-435 and MDA-MB-231 breast tumour cell lines as well as in the HB4aC3.6 normal cell line." (PMID 20109227, 2010). "A longer disease-free survival is experienced in patients showing ESR1 gene amplification in breast tumors compared to those without this alteration." (PMID 39329990, 2024). "Estrogen receptor α (ERα; ESR1), a member of the steroid hormone receptor family, is a hormone-activated transcription factor that is essential for both physiologic mammary gland homeostasis and pathologic breast tumor development." (PMID 37883178, 2024). "We initiated this project because it was clear from breast tumour RNA‐Seq data that there were both exons and alternative splicing events in the ESR1 locus that were not present in GENCODE or RefSeq, the main transcript annotation databases." (PMID 37676103, 2023). "Additional potential driver alterations noted in the brain metastases (but not presented in the matched primary breast tumor) included CDK2NA loss in addition to PI3KCA and ESR1 mutations." (PMID 37377606, 2023). "Enrichment was found among genes up regulated in early primary breast tumors expressing ESR1 vs the ESR1 negative ones." (PMID 36584096, 2022). "IHC is currently the gold standard method in routine pathological diagnosis, including the semiquantitative determination of Estrogen Receptor 1 (ESR1), Progesterone Receptor (PGR) and Human Epidermal Growth Factor Receptor 2 (HER2) receptor status in breast tumors." (PMID 34408238, 2021). "For example, protein levels of CCNB1 (cyclin B1) were significantly higher (P = 7.28E‐13) in breast tumors with alterations in FAM83 family genes, whereas protein levels of GATA3 (P = 3.79E‐07), PGR (P = 5.77E‐07), and ESR1 (P = 9.20E‐07) were significantly lower." (PMID 28078827, 2017). "Our data mining analysis using the METABRIC dataset did reveal a significant negative correlation between HYAL1 and ESR1 genes in breast tumors, providing a clinical relevance to the direct down-regulation of HYAL1 by estrogen." (PMID 27764788, 2016). "More potent ESR1 antagonists, such as AZD9496, have recently been reported to be more effective than fulvestrant (even used at supra-clinical doses) or tamoxifen in pre-clinical ESR1 mutant breast tumour models." (PMID 27801670, 2016). "The methylation of three of them (ESR1, MGMT and WT1) has been widely reported in breast tumors." (PMID 22011321, 2011).